RNF207 (ring finger protein 207)
Description:
Plays a role in cardiac repolarization possibly by stabilizing membrane expression of the potassium channel KCNH2/HERG, or by assisting its synthesis, folding or export from the endoplasmic reticulum, in a heat shock protein-dependent manner.
Synonyms: C1orf188; FLJ46380; FLJ32096
Tractability: No criterion of Open Targets' tractability assessment is met for any kind of drug.
Gene: Protein-coding gene on chromosome 1 (6,205,392 to 6,221,299, forward strand). Ensembl gene ENSG00000158286.
Subcellular location: Cytoplasm
Subcellular location (Human Protein Atlas): Cytosol
Gene Ontology:
Molecular function: Hsp70 protein binding; protein binding; protein-folding chaperone binding; transmembrane transporter binding; metal ion binding; zinc ion binding
Biological process: positive regulation of gene expression; positive regulation of membrane repolarization during ventricular cardiac muscle cell action potential; positive regulation of membrane repolarization during cardiac muscle cell action potential; regulation of cardiac muscle contraction; regulation of heart looping
Cellular component: cytoplasm; perinuclear region of cytoplasm
Genetic constraint (gnomAD): Loss-of-function variants: 67 observed, 64.28 expected, observed/expected ratio (o/e) 1.04, 90% interval 0.86 to 1.28. The upper end of that interval is the gene's LOEUF score, 1.28, which puts it in group 5 of 6, group 1 being the genes least tolerant of losing a copy. Missense variants: 893 observed, 730.01 expected, observed/expected ratio (o/e) 1.22, 90% interval 1.16 to 1.29. Synonymous variants: 333 observed, 295.91 expected, observed/expected ratio (o/e) 1.13, 90% interval 1.03 to 1.23.
Homologues: Orthologues: chimpanzee RNF207 (99% identical), macaque RNF207 (96% identical), dog RNF207 (83% identical), pig RNF207 (83% identical), rat Rnf207 (82% identical), mouse Rnf207 (81% identical), tropical clawed frog rnf207 (63% identical), zebrafish rnf207b (59% identical), rabbit RNF207 (55% identical), Caenorhabditis elegans F47G9.4 (27% identical), zebrafish rnf207a (18% identical).
Diseases named in the same sentence as RNF207 in open-access papers:
RNF207 is named in the same sentence as 17 diseases in open-access papers, as found by Europe PMC text mining. Sharing a sentence is not in itself a finding about the gene and the disease. The quoted sentences say what the papers report.
cardiac hypertrophy (3 papers, 2023 to 2025). "RNF207 encodes the really interesting new gene (RING)-finger protein 207 (RNF207), which has proposed actions in regulating the cardiac action potential and is involved in pathways known to regulate cardiac hypertrophy." (PMID 40080479, 2025). "RNF207 encodes a heart-specific really interesting new gene (RING) finger protein that has been shown to interact with the voltage-dependent anion channel (VDAC) 1, regulate the repolarizing channel HERG and is involved with pathological cardiac hypertrophy." (PMID 40080479, 2025). "Interestingly, RNF207 was shown to interact with TAB1, a protein that activated pathways related to cardiac hypertrophy and, in another study, accumulated in nuclei and intercalated disks of isolated rat cardiomyocytes." (PMID 37723491, 2023).
Long QT syndrome (3 papers, 2022 to 2025). "Additionally, it has been shown in humans that abnormal function of the RNF207 protein is implicated in or can worsen the expression of long-QT syndrome, known to result in ventricular arrhythmias causing syncope and sudden death." (PMID 40080479, 2025). "For example, monitoring of Rnf207, which is implicated in Cardiac K channel regulation, may provide new insights in the diurnal variation of Long QT syndrome and syncope." (PMID 35264172, 2022). "From this candidate gene list, CACNA1D and RNF207 were already described to be associated with inherited cardiac conditions (CACNA1D: sinoatrial node dysfunction; RNF207: Long-QT Syndrome (LQTS))." (PMID 36430690, 2022).
endometrial cancer (2 papers, 2023). Primary or metastatic malignant neoplasm involving the endometrium (mucous membrane that lines the endometrial cavity). "Vanessa’s study found that the expression of RNF207 was upregulated in endometrial cancer, and its expression was higher in lymph node-positive patients than in lymph node-negative patients." (PMID 37654657, 2023). "RNF207 was found to predict lymph node involvement in patients with obesity and endometrial cancer." (PMID 37143720, 2023).
high blood pressure (2 papers, 2023 to 2024). "An increase in IGFBP5 and a decrease in RNF207 RNA levels were identified as markers of cardiac injury related to high blood pressure, based on a whole transcriptome analysis in the mouse." (PMID 39796124, 2024). "Transcript levels for genes linked to cardiac damage, including hypertrophy (ANP and BNP), cardiac fibrosis (COL I and COL III), and hypertension-related injury (IGFBP5 and RNF207), were determined by qPCR." (PMID 39796124, 2024). "As markers of cardiac injury related to high blood pressure, we also measured insulin-like growth factor binding protein 5 (IGFBP5) and ring finger protein 207 (RNF207) levels that were previously identified through whole transcriptome analysis in the mouse." (PMID 39796124, 2024). "RNF207 had no significant variants, and PRKAA2 was linked to several phenotypes involving myocardial ischemia, hypertension, and lipid metabolism." (PMID 37723491, 2023).
Ventricular arrhythmia (2 papers, 2015 to 2025). "It is reported that genetic variation in RNF207 may influence the duration of QT interval that could predisposes to ventricular arrhythmias and sudden cardiac death (SCD)." (PMID 25599194, 2015).
cervical clear cell carcinoma (1 paper, 2023). "Herein, we used comparative analysis to screen out genes with large differences in expression between HPV-negative and HPV-positive cervical clear cell carcinoma patients, including ALKBH7, MYCBP, MZF1, RNF207, RRS1, and TUSC2." (PMID 37654657, 2023).
congestive heart failure (1 paper, 2025). Failure of the heart to pump a sufficient amount of blood to meet the needs of the body tissues, resulting in tissue congestion and edema. "Also it has been shown that RNF207 plays an important role in the production of ATP in cardiomyocytes, and that dysfunction in this protein may worsen the development of congestive heart failure." (PMID 40080479, 2025).
coronary heart disease (1 paper, 2015). "We examined the plasma Rnf207, Fbxo32, Trim54, Trim63, Kbtbd10 and Asb11 in three groups (the AMI, coronary heart disease (CHD) and healthy groups)." (PMID 25599194, 2015).
dilated cardiomyopathy (1 paper, 2025). Cardiomyopathy which is characterized by dilation and contractile dysfunction of the left and right ventricles. "Association of the RNF207 variant with dilated cardiomyopathy." (PMID 40080479, 2025).
neuroblastoma (1 paper, 2015). Neuroblastoma (NB) is the most common solid, extracranial childhood tumor. "RNF207 was also recently identified as a tumor suppressor in neuroblastomas." (PMID 26039411, 2015).
RNF207 also shares sentences with these, for which no sentence is quoted: cardiomyopathy (2 papers); Hypertension (2); colorectal cancer (1); heart diseases (1); myocardial ischemia (1); Obesity (1); tumor (1).